PTPN4 (protein tyrosine phosphatase non-receptor type 4)
Description:
Phosphatase that plays a role in immunity, learning, synaptic plasticity or cell homeostasis. Regulates neuronal cell homeostasis by protecting neurons against apoptosis. Negatively regulates TLR4-induced interferon beta production by dephosphorylating adapter TICAM2 and inhibiting subsequent TRAM-TRIF interaction. Also dephosphorylates the immunoreceptor tyrosine-based activation motifs/ITAMs of the TCR zeta subunit and thereby negatively regulates TCR-mediated signaling pathway (By similarity). May act at junctions between the membrane and the cytoskeleton.
Synonyms: MEG; PTPMEG; PTPMEG1
Tractability: Small molecule: it has a binding pocket of medium quality. Antibody: UniProt places it where antibodies can reach, with high confidence; its Gene Ontology location is reachable by antibodies, with medium confidence; the Human Protein Atlas places it where antibodies can reach. PROTAC: a small molecule that binds it is known.
Target class: Tyrosine protein phosphatase; Enzyme; Phosphatase; Protein Phosphatase
Gene: Protein-coding gene on chromosome 2 (119,759,604 to 119,984,899, forward strand). Ensembl gene ENSG00000088179.
Subcellular location: Cell membrane; Cytoplasm, cytoskeleton; Cytoplasm
Subcellular location (Human Protein Atlas): Nucleoplasm; Cytosol; Plasma membrane
Pathways (Reactome):
Immune System: Interleukin-37 signaling; Toll Like Receptor 4 (TLR4) Cascade
Gene Ontology:
Molecular function: protein binding; non-membrane spanning protein tyrosine phosphatase activity; protein tyrosine phosphatase activity; cytoskeletal protein binding; glutamate receptor binding
Biological process: protein dephosphorylation
Cellular component: cytoplasm; cytoplasmic side of plasma membrane; plasma membrane; cytosol; nucleoplasm; cytoskeleton; membrane
Genetic constraint (gnomAD): Loss-of-function variants: 37 observed, 98.21 expected, observed/expected ratio (o/e) 0.38, 90% interval 0.29 to 0.5. The upper end of that interval is the gene's LOEUF score, 0.5, which puts it in group 2 of 6, group 1 being the genes least tolerant of losing a copy. Missense variants: 723 observed, 915.37 expected, observed/expected ratio (o/e) 0.79, 90% interval 0.74 to 0.84. Synonymous variants: 275 observed, 317.25 expected, observed/expected ratio (o/e) 0.87, 90% interval 0.79 to 0.96.
Homologues: Orthologues: chimpanzee PTPN4 (99% identical), macaque PTPN4 (99% identical), dog PTPN4 (97% identical), rabbit PTPN4 (97% identical), pig PTPN4 (96% identical), rat Ptpn4 (95% identical), guinea pig PTPN4 (95% identical), mouse Ptpn4 (95% identical), tropical clawed frog ptpn4 (84% identical), zebrafish ptpn4a (80% identical), zebrafish ptpn4b (72% identical). Paralogues in human: PTPN3 (52% identical), PTPRF (22% identical), PTPRD (21% identical), PTPRS (21% identical), PTPRB (21% identical), PTPRT (20% identical), PTPRK (20% identical), PTPRM (20% identical), PTPN13 (19% identical), PTPN23 (19% identical), PTPN21 (19% identical), PTPRZ1 (19% identical), and 23 more.
Diseases named in the same sentence as PTPN4 in open-access papers:
PTPN4 is named in the same sentence as 37 diseases in open-access papers, as found by Europe PMC text mining. Sharing a sentence is not in itself a finding about the gene and the disease. The quoted sentences say what the papers report.
prostate carcinoma (5 papers, 2022 to 2025). A carcinoma that arises from epithelial cells of the prostate gland. "For instance, elevated miR‐375 promotes cell proliferation, invasion, and induces enzalutamide resistance in prostate cancer cells by targeting PTPN4, which in turn enhancing the phosphorylation of STAT3." (PMID 40145330, 2025). "Of note, PTPN4 was suppressed in prostate cancer tissues in the UALCAN database, which was negatively correlated with miR-375 expression, as illustrated in StarBase." (PMID 36042375, 2022). "In summary, this is the first proof of principle study that shows that miR-375 can facilitate prostate cancer progression and enzalutamide resistance via the PTPN4/STAT3 pathway." (PMID 36042375, 2022). "Nonetheless, PAFAH1B2 expression has been reported as a prognostic marker for MM in validation analysis while PTPN4 has been found to serve as an upstream therapeutic target in the treatment of prostate cancer, indicating the potential for the two proteins as future research entry points." (PMID 37775746, 2023). "In KEGG analysis, PTPN4 was significantly related to prostate cancer and miRNAs in cancer." (PMID 36042375, 2022). "MiR-375 directly interfered with the expression of PTPN4, which in turn stabilized phosphorylated STAT3 in castration-resistant prostate cancer." (PMID 36556168, 2022). "Targeting miR-375 with e-375i could inhibit prostate cancer cell proliferation, migration, and invasion, and promote cell apoptosis and enzalutamide drug sensitivity in prostate cancer via down-regulating STAT3 expression by up-regulating PTPN4 expression." (PMID 36969009, 2023). "Other than PTPN4, no statistical significance was found regarding EIF4G3 or UBE3A expression when prostate cancer tissues were compared to normal tissues in the UALCAN database." (PMID 36042375, 2022).
breast carcinoma (4 papers, 2022 to 2025). "PTPN11, for example, has been linked to pancreatic cancer, and PTPN4 has been linked to breast cancer." (PMID 37359510, 2023). "However, most PTPN family members function as tumor suppressors in breast cancer, including PTPN2, PTPN4, PTPN6, PTPN9, PTPN13, PTPN14, and PTPN23." (PMID 35957898, 2022).
glioblastoma (4 papers, 2018 to 2024). The most malignant astrocytic tumor (WHO grade IV). "It has also been shown that silencing of PTPN4 can induce the apoptosis of glioblastoma, but fewer studies focus on the role of PTPN4 in myocardial infarction." (PMID 34306144, 2021). "In neuroblastoma and glioblastoma cell lines, mitogen-activated protein kinase p38γ served as a cellular partner of PTPN4." (PMID 31178952, 2019). "The PDZ domain-regulated impact of PTPN4 on glioblastoma cell survival points to the modulation of PDZ-dependent PPIs as an attractive cancer treatment option." (PMID 29439552, 2018). "Upon ligand binding, the PDZ-mediated inhibition is released and PTPN4 no longer protects glioblastoma cells from apoptosis." (PMID 29439552, 2018).
neuroblastoma (2 papers, 2019 to 2021). Neuroblastoma (NB) is the most common solid, extracranial childhood tumor. "Other non-receptor PTPs related with neuroblastoma include PTPN4, PTPN9, and PTPN12." (PMID 34957126, 2021).
pancreatic cancer (2 papers, 2023 to 2025). "Besides, MARCH8 facilitated the proliferation and metastasis of pancreatic cancer by inducing the degradation of PTPN4 protein and thereby activating the STAT3 phosphorylation." (PMID 40145330, 2025).
acromegaly (1 paper, 2015). Acromegaly is an acquired disorder related to excessive production of growth hormone (GH) and characterized by progressive somatic disfigurement (mainly involving the face and extremities) and systemic manifestations. "We also identified several novel transcriptional changes, some of which may be important for GH/IGF responses (PTPN3 and PTPN4) and the effects of acromegaly on growth and proliferation." (PMID 26087292, 2015).
cervical cancer (1 paper, 2013). A primary or metastatic malignant neoplasm involving the cervix. "From the genes differentially expressed between early and advanced stages of cervical cancer, six genes – three upregulated (BCL3, IGF2, and PIK3R1) and three downregulated (PTPN4, PERP, and DUSP1) were selected for validation by qRT-PCR." (PMID 24403257, 2013).
colorectal cancer (1 paper, 2020). A primary or metastatic malignant neoplasm that affects the colon or rectum. "CCLE analyses showed that in esophagus cancer cell lines, PTPN1, PTPN4 and PTPN12 were highly expressed; in gastric cancer cell lines, PTPN2 and PTPN12 were highly expressed; in colorectal cancer cell lines, PTPN12 was highly expressed while PTPN22 was downregulated." (PMID 32536826, 2020).
Huntington disease (1 paper, 2022). Huntington disease (HD) is a rare neurodegenerative disorder of the central nervous system characterized by unwanted choreatic movements, behavioral and psychiatric disturbances and dementia. "Only one of these phosphopeptides was significantly different between WT and Huntington’s disease mice in SH conditions: tyrosine-protein phosphatase non-receptor type 4 (PTPN4), at Serine 899 (no known functional annotation or upstream regulator)." (PMID 36523271, 2022).
ischemia (1 paper, 2021). A hypoperfusion of the BLOOD through an organ or tissue caused by a PATHOLOGIC CONSTRICTION or obstruction of its BLOOD VESSELS, or an absence of BLOOD CIRCULATION. "MiR-181c-5p could down-regulate PTPN4 to promote the inflammatory response during ischemia/reperfusion injury, and also could regulates ischemia/reperfusion injury-induced neuronal cell death by targeting c-Fos42,43." (PMID 34400675, 2021).
oral squamous cell carcinoma (1 paper, 2022). "PTPN4 appears to function as a tumor suppressor in cancer, miR-15b-5p activates STAT3 signaling by targeting PTPN4 to promote oral squamous cell carcinoma progression." (PMID 35957898, 2022).
osteosarcoma (1 paper, 2019). A usually aggressive malignant bone-forming mesenchymal neoplasm, predominantly affecting adolescents and young adults. "Indeed, silencing of PTPN4 or p38γ gene leads to massive cell death in human osteosarcoma cells." (PMID 31178952, 2019).
ovarian carcinoma (1 paper, 2025). A malignant neoplasm originating from the surface ovarian epithelium. "The interaction between KPNA5 and PTPN4 was further confirmed by co‐IP and Western blot in ovarian cancer cells." (PMID 40145330, 2025). "In this study, we found that PTPN4 is a key cargo protein of KPNA5 in ovarian cancer cells by mass spectrometry analysis of KPNA5‐bound proteins." (PMID 40145330, 2025). "Although a few studies have suggested that PTPN4 could function as a tumor suppressor gene, its role in ovarian cancer is unclear." (PMID 40145330, 2025). "Moreover, overexpression of KPNA5 could significantly promote the transport of PTPN4 from cytoplasm to nucleus in ovarian cancer cells." (PMID 40145330, 2025). "Here, we found that the expression of wild‐type PTPN4 significantly inhibited the proliferation and invasive ability of ovarian cancer cells, but mutant PTPN4 with the deletion of the NLS sequence failed to induce significant tumor suppression." (PMID 40145330, 2025). "In addition, along with other studies, we also found that PTPN4 functions as a tumor suppressor in OC mainly by inhibiting the phosphorylation of STAT3, which may further hinder the activation of the subsequent pathway and inhibit ovarian cancer tumor growth and metastasis." (PMID 40145330, 2025).
pancreatic ductal adenocarcinoma (1 paper, 2022). An infiltrating adenocarcinoma that arises from the epithelial cells of the pancreas. "PTPN4 expressed higher in pancreatic ductal adenocarcinoma with a fold change of 1.625 versus normal samples." (PMID 35154122, 2022).
papillary thyroid cancer (1 paper, 2023). "Crocin, a saffron-derived pigment, triggers the ROS-dependent apoptosis of papillary thyroid cancer cells by downregulating the miR-34a-5p and upregulating its target, protein tyrosine phosphatase non-receptor type 4 (PTPN4)." (PMID 36612314, 2023).
rectal cancer (1 paper, 2025). A primary or metastatic malignant neoplasm that affects the rectum. "Additionally, PTPN4 suppresses the growth of rectal cancer cells through dephosphorylating pSTAT3 at the Tyr705 residue." (PMID 40145330, 2025). "In addition, PTPN4 could suppress rectal cancer cell growth by dephosphorylating pSTAT3 at the Tyr705 residue, thereby impairing the transcriptional activity of STAT3." (PMID 40145330, 2025).
SARS-CoV infections (1 paper, 2021). "Interestingly, while PTPN4 acts as an inhibitor, the TLR4 signaling pathway is activated by the SARS-CoV-2 spike protein, and mice lacking TLR4 had more severe SARS-CoV infections than wild-type mice." (PMID 34070971, 2021).
cancer (12 papers, 2015 to 2025). A tumor composed of atypical neoplastic, often pleomorphic cells that invade other tissues. "Then, the correlation between methylation and survival index (OS, DSS, DFI, PFS) in pan-cancer was evaluated, and the results indicated that the methylation upregulation of PTPN4 was a risk factor of UVM." (PMID 37884566, 2023). "Lastly, PTPN4 belongs to the superfamily of protein tyrosine-kinases and phosphatases, frequently mutated in cancers." (PMID 31366136, 2019). "Recently, several studies have found that PTPN4 can function as a tumor suppressor in various cancers." (PMID 40145330, 2025). "Lastly, PTPN4, a PLR-associated gene, plays a role in immunity via cellular signaling and cell death prevention and has been previously linked to various cancers." (PMID 37950349, 2024). "Mutations in other cancer‐associated genes such as MAGI3, TSC1, PTPN4, RAB3IP, and RYR1 were also identified." (PMID 26432421, 2015). "Recently, a growing number of evidence have demonstrated that PTPN4 expression is downregulated in multiple types of cancers, which indicates that PTPN4 may function as a tumor suppressor." (PMID 40145330, 2025). "For example, hsa-miR-183-5p was found to inversely regulate PTPN4, serving as a therapeutic target to suppress the metastatic potential in NSCLC patients, and hsa-let-7c-5p was verified to prevent cancer metastasis by degrading its bridging hub ceRNA, MAP4K3." (PMID 36084156, 2022). "In gastric tissue, the expression of PTPN4, PTPRA, and PTPRS were increased in cancer tissue compared with normal tissue." (PMID 30126387, 2018).
tumor (8 papers, 2009 to 2025). "We analyzed the expression levels of PTPNs in the TCGA database and discovered that PTPN1, PTPN6, PTPN7, PTPN18, PTPN20, and PTPN22 were significantly upregulated in tumor samples, while PTPN4, PTPN5, PTPN10, PTPN11, PTPN13, PTPN14, and PTPN21 were downregulated in tumor samples." (PMID 36226189, 2022). "Together with the finding that PTPN4 acts as a tumor inhibitor, it is suggested that miR-375 may play an important role in miRNA-mediated PCa progression by negatively regulating PTPN4." (PMID 36042375, 2022). "In our research, the results indicated that PTPN3, PTPN4, PTPN5 expression in normal tissues was lower than in PAAD tissues, but the tumor stage of PAAD patients did not affect the expression." (PMID 35154122, 2022). "Two more CpG islands corresponding to genes PTPN4 and RALB were also analysed but remained unmethylated in all the normal and tumour samples (data not shown)." (PMID 19384295, 2009).
neurodevelopmental disorder (3 papers, 2020 to 2025). A behavioral and cognitive disorder with onset during the developmental period that involves impaired or aberrant development of intellectual, motor, or social functions. "This approach identified two class 1 genes: PPP2CA and PTPN4, for which multiple variants have recently been reported as being linked to neurodevelopmental disorders, validating our approach." (PMID 37056996, 2023).
infectious disease (1 paper, 2022). A disorder directly resulting from the presence and activity of a microbial, viral, or parasitic agent in humans. "In addition, the involvement of the tyrosine protein phosphatase nonreceptor type 4 protein, encoded by the PTPN4 gene, in infectious diseases was also proven that also plays a role in immunity and cell homeostasis." (PMID 35504997, 2022).
PTPN4 also shares sentences with these, for which no sentence is quoted: cognitive deficits (1 paper); developmental delay (1); esophagus cancer (1); gastric cancer (1); hepatocellular carcinoma (1); lentivirus infection (1); leukemia (1); memory impairment (1); myocardial infarction (1); neurological diseases (1); osteoporosis (1); psychiatric disorder (1); Rett syndrome (1); schizophrenia (1); stomach cancer (1); thyroid cancer (1).